RN7SL132P (RNA, 7SL, cytoplasmic 132, pseudogene)
Gene: Miscellaneous RNA gene on chromosome 7 (34,753,424 to 34,753,719, forward strand). Ensembl gene ENSG00000242653.
Homologues: Orthologues: chimpanzee Metazoa_SRP (99% identical), macaque Metazoa_SRP (92% identical). Paralogues in human: RN7SL2 (80% identical), RN7SL1 (79% identical), RN7SL3 (79% identical), RN7SL126P (77% identical), RN7SL408P (77% identical), RN7SL296P (76% identical), RN7SL426P (76% identical), RN7SL147P (76% identical), RN7SL398P (76% identical), RN7SL650P (76% identical), RN7SL664P (76% identical), RN7SL679P (76% identical), and 701 more.